IL6 (interleukin 6)
Diseases named in the same sentence as IL6 in open-access papers (continued):
Sharing a sentence is not in itself a finding about the gene and the disease.
urinary tract infection (38 papers, 2009 to 2025). "Urinary tract infections cause the secretion of IL-6 and IL-8 by urinary tract epithelial cells, facilitating the migration of neutrophils to the infected region." (PMID 38778291, 2024). "Surgery spreads the primary urinary tract infection, causing excessive release of a large number of inflammatory cytokines (such as IL-6, IL-8, and TNF-α)." (PMID 34422076, 2021). "Induction of IL-6 in human bladder smooth muscle cells by fatty acids may represent a pathogenetic factor underlying the higher frequency and persistence of urinary tract infections in patients with metabolic diseases." (PMID 20526368, 2010). "Three metabolites showed similar causal effects on different inflammatory markers or infectious phenotypes, stearidonate (18:4n3) was negatively related to SAA1 and urinary tract infections, and 5-oxoproline contributed to elevated IL-6 and SAA1 levels." (PMID 38585702, 2024). "Undoubtedly, the involvement of the JAK/STAT pathway in bladder pathologies deserves further investigation, as the deactivation of the IL6/STAT3 signaling has been shown to impair the antimicrobial response in urinary tract infection." (PMID 36982831, 2023). "The prognostic value of urinary IL-6 levels was substantiated in a recent meta-analysis that identified urinary IL-6 concentrations as appropriate to detect febrile urinary tract infections in children and to distinguish them from other febrile conditions." (PMID 37189804, 2023). "Mechanistically, bacteria mediate an immune response in patients with urinary tract infections due to the release of proinflammatory cytokines such as interleukin 6 (IL-6) and interleukin 8 (IL-8)." (PMID 36498652, 2022). "Release of IL-6 and IL-8 have been considered markers for urinary tract infection, with the presence of these cytokines correlating with symptomatic urinary tract infection (UTI) in elderly patients." (PMID 33657181, 2021). "Multivariate analysis had shown that NIHSS score, interleukin-6, and hemoglobin were independent influencing factors affecting urinary tract infection." (PMID 32629702, 2020). "The area under the ROC curve of NIHSS score, interleukin-6, and hemoglobin for urinary tract infection was 0.711 (95% CI: 0.607 to 0.815), 0.661 (95% CI: 0.546 to 0.777), and 0.625 (95% CI: 0.510 to 0.740), respectively." (PMID 32629702, 2020). "Multivariate Logistic regression analysis showed that sex, smoking, NIHSS score, interleukin-6, and hemoglobin were independent influencing factors of urinary tract infection." (PMID 32629702, 2020). "Urinary tract infections are typically accompanied by an innate immune response involving vigorous IL-6 and IL-8 production." (PMID 24098552, 2013). "With the second search (“urinary tract infection” with “PCT” or “IL-6” or “IL-8”), six additional articles were retrieved." (PMID 19707519, 2009). "We identified procalcitonin (PCT), interleukin 6 (IL-6) and interleukin 8 (IL-8) as potential novel biomarkers for diagnosing urinary tract infection and assessing the severity of infection." (PMID 19707519, 2009). "However, individuals with higher IL‐6 postdelivery were more likely to have a urinary tract infection or have a non‐elective C‐section." (PMID 40844502, 2025). "In addition, P2Y2R regulates IL-6 and IL-8 release from renal epithelial cells in bacteria-induced urinary tract infections, suggesting its contribution to innate immune responses." (PMID 39684275, 2024). "Urinary IL-6 levels may have the potential to monitor therapeutic success in children with urinary tract infections." (PMID 37189804, 2023). "The decrease in IL-6 was also the most pronounced in urinary tract infections (93.8%), followed by skin and soft tissue infection (80.42%), abdominal cavity infection (79.29%), and pulmonary infection (23.64%), and showed the least significant decrease in blood infection (0%)." (PMID 36249210, 2022).
urinary tract infection (continued). "Furthermore, NIHSS score at a cutoff value of 3.5 exhibited the best balance between sensitivity and specificity for detection of urinary tract infection, followed by interleukin-6 (cutoff value, 4.910 pg/mL) and hemoglobin (cutoff value: 123.50 g/L)." (PMID 32629702, 2020). "A new serum marker of inflammation copeptin (CPP) a stable C-terminal pro-vasopressin was assessed along with conventional markers such as C-reactive protein (CRP), procalcitonin (PCT) and IL-6 to discriminate between lower and upper bacterial urinary tract infections (UTI)." (PMID 26152182, 2015). "IL-6 and IL-1β have been found to be increased in inflammatory urinary tract disease, indicating that IL-6 may also play an essential role in bladder dysfunction related to urinary tract infection." (PMID 29204439, 2017). "The hs-CRP in the serum of children with urinary tract infection was 98.21±19.27 mg/mL, and the values of PCT, IL-6, TNF, and IFN-γ were 4.713±1.488 ng/mL, 422.7±160.0 pg/mL, 1.908±0.1966 pg/mL, and 37.22±15.05 pg/mL, respectively." (PMID 37534327, 2023). "We previously reported a pathological role for systemic interleukin 6 (IL-6) in mediating frontal and hippocampal neuronal injury in murine models of VILI and urinary tract infection." (PMID 36405620, 2022). "And the predictive model for urinary tract infection (including sex, NIHSS, interleukin-6, and hemoglobin) have the best predictive effect." (PMID 32629702, 2020). "Children with urinary tract infections had grossly elevated urinary IL-6 levels compared to children without bacteriuria." (PMID 37189804, 2023). "Elevated interleukin-6, higher NIHSS, and decreased hemoglobin may be used to predict urinary tract infection." (PMID 32629702, 2020). "Although elevated levels of urinary cytokine IL-2 were associated with a favorable response to intravesical BCG, elevated levels of the non-specific cytokines IL-6 and IL-8 were observed due to concurrent urinary tract infections." (PMID 31216733, 2019). "Hence, children with urinary tract infections lacked an elevation of serum IL-6 levels." (PMID 37189804, 2023). "In the laboratory test results, the levels of interleukin-6 and procalcitonin in patients with urinary tract infection were higher than those in patients without infection, and the levels of hemoglobin in patients with urinary tract infection were lower than patients without infection." (PMID 32629702, 2020). "As a result, an inverse relationship between serum 25(OH)D and urine IL-6/creatinine (p < 0.05) as well as between serum 25(OH)D and KIM-1/creatinine (p < 0.05) in kidney transplant recipients without rejection or urinary tract infection were detected." (PMID 28245293, 2017). "Patients who developed wound infection showed a higher IL-6 concentration on POD 2 (42.56 versus 30.02 ng/ml, p = 0.03), POD 3 (36.52 versus 23.62 ng/ml, p = 0.06) and POD 4 (34.43 versus 19.99 ng/ml, p = 0,046), while pulmonary and urinary tract infections had no impact on ip IL-6-levels." (PMID 26444274, 2015).
abdominal aortic aneurysm (37 papers, 2009 to 2025). Enlargement and ballooning of the vessel that supplies arterial blood to the abdomen, pelvis and legs. "Accordingly, the IL6 -572GG genotype was associated with lower risks of kidney allograft survival and abdominal aortic aneurysm, consistent with our data showing a lower risk of CKD in GG genotype carriers." (PMID 22230215, 2012). "The incidences of post-implantation syndrome vary widely between 14% and 60% for abdominal aortic aneurysm and intervention was suggested to cause white cell activation with the release of various cytokines, such as IL-1, IL-6, and TNF-α." (PMID 22655044, 2012). "It has been shown in a mouse model of abdominal aortic aneurysm that mice exposed to nicotine displayed higher miR-21 levels, which was associated with a reduction in tumor suppressor genes, as well as with an augmentation of inflammatory genes such as IL-6 and MCP-1." (PMID 28993685, 2017). "Formerly, it was elaborated that miR-155 triggers expression of macrophages and cytokines; TNFα, and IL-6 in abdominal aortic aneurysm in mice, and there was a significant positive correlation among the three of them." (PMID 39798064, 2025). "Previous studies have shown that circulating levels of IL-6 correlate with the progression of abdominal aortic aneurysms." (PMID 40599317, 2025). "Previous studies have demonstrated that in human abdominal aortic aneurysms, IL6 increased NOX activity and MALAT1 expression in a time-dependent manner, leading to excessive ROS production." (PMID 35692503, 2022). "Recent studies have also confirmed its role in abdominal aortic aneurysms, Here, we demonstrated the role of IL-6 and IL-1B in TAAA disease." (PMID 34202072, 2021). "The level of IL-6 was increased in the vessel wall of abdominal aortic aneurysms in AngII-infused ApoE-/- mice compared to similar sections of aorta in saline-infused control mice." (PMID 32362823, 2020). "In human abdominal aortic aneurysm, IL-6 induced the activity of NOX2 in the aortic endothelial cells via the induction of the lncRNA MALAT1 by an ERK-dependent mechanism." (PMID 32929606, 2020). "Abdominal aortic aneurysms of non IgG4 origin or of atherosclerotic origin also showed increased serum IL-6 compared to normal controls." (PMID 30883599, 2019). "Both thoracic and abdominal aortic aneurysms are positively correlated to high circulating levels of IL-6." (PMID 29158612, 2017). "carried out a small case-control study, and indicated a significant increase in blood IL-6 after reperfusion in aortic abdominal aneurysm surgery patients, which was followed by a significant reduction of lung function." (PMID 26502877, 2015). "Recently, a study indicated a cytokine-induced tissue inflammation in the pathogenesis of abdominal aortic aneurysms, and it has been documented that circulating IL-6 levels increase in these patients." (PMID 19551157, 2009). "Glutamine protected against mouse abdominal aortic aneurysm through inhibiting M1 macrophage activation, secretion of IL-6 and TNF-α by macrophage, release of MMP-9 by RAW264.7 (macrophage) and MMP-2 by MOVAS (SMC), as well as apoptosis of vascular SMC by ROS and MMP." (PMID 38903916, 2024). "Furthermore, there has been anoted elevation in IL-6 levels within the tissues of individuals afflicted with abdominal aortic aneurysms and intracranial aneurysms." (PMID 38313677, 2024). "EP4 stimulation increased IL-6 production via PKA-NF-κB pathways in vascular smooth muscle cells isolated from the mouse aorta and human abdominal aortic aneurysms." (PMID 36438844, 2022). "In addition, a recent study noted that knockdown of PVT1 decreased levels of MMP-2 and MMP-9, augmented TIMP-1 expression, and suppressed serum levels of TNF-α, IL-1β, and IL-6 in VAMC and ApoE-/- mice of abdominal aortic aneurysm model." (PMID 34775377, 2021).
abdominal aortic aneurysm (continued). "Also, our study confirmed that the expression of inflammatory factors IL-6, IL-17, and TNF was significantly increased in abdominal aortic aneurysm samples compared with adjacent aorta samples." (PMID 33362847, 2020).
Atrophy (37 papers, 2011 to 2026). Any weakening or degeneration, especially through lack of use. "The proximal tubule epithelial cells produce and release pro-inflammatory cytokines such as TNFα and IL6, this contributing to the extent of interstitial fibrosis, tubular atrophy, glomerulosclerosis, glomerular loss and CKD." (PMID 27031710, 2016). "In fact, the overexpression of IL-6 in transgenic mice caused muscular atrophy and increased levels of cathepsin in skeletal muscle, indicating that IL-6 is involved in the regulation of muscle protein degradation." (PMID 27330885, 2016). "The increase of IL-6 levels in addition to the thymic atrophy and damage of the spleen caused by S. aureus infection, only seemed to decrease in the case of the BV-loaded CS-NPs treated group, which had average spleen and thymus sections and an IL-6 level that was very close to the negative control." (PMID 37081055, 2023). "However, IL-6 expression is increased during recovery from cast-immobilization induced atrophy in rats, and IL-6-deficient mice display prolonged recovery from atrophy induced by hind limb suspension." (PMID 34456749, 2021). "However, the miRNA-target networks associated with IL6-induced muscle atrophy remain to be characterized." (PMID 34944037, 2021). "The results showed that IL-6 levels in the group treated with WBM decreased compared to the atrophy group (p<0.05)." (PMID 39086863, 2024). "An increase in IL-6 expression in skeletal muscle has been observed in several models of muscle atrophy." (PMID 35408999, 2022). "IL-6 was proved to be involved in tubulointerstitial fibrosis, tubular atrophy, acute and chronic lesions in immune renal diseases, like LN, in metabolic, ischemic, toxemic diseases." (PMID 34205600, 2021). "Biomarkers of inflammation, such as interleukin 6 (IL-6) and TNF-α, have been associated with muscle atrophy in both human and animal studies and age-related cognitive decline in humans." (PMID 33383820, 2020). "For instance, IL-6, IL-8, and RANTES have been associated with the risk of clinical relapses, radiological activity (e.g., lesions, atrophy), treatment switch, and disability progression after up to 6 years." (PMID 31569668, 2019). "Studies using unloading-induced atrophy model have shown that the expression of IL-6 is elevated in the immobilized muscles or skins." (PMID 29351340, 2018). "Some scholars believe that NF-κB activation-induced muscle atrophy may be related to the increase of inflammatory factors such as TNF-α and IL-6, and blocking this pathway may represent a promising target to treat muscle atrophy." (PMID 38509497, 2024). "Our next studies will focus on the role and mechanisms of IL-6 downstream transcription factors in the occurrence of muscle atrophy, endeavoring to discover new targets of muscle atrophy treatment beyond suppressing inflammation and enhancing mitochondrial function." (PMID 34552592, 2021). "Furthermore, supraphysiological levels of IL-6, sIL6R, and palmitate as representative of free FAs resulted in additive levels of atrophy." (PMID 33851955, 2021). "However, it is also known that chronically elevated IL-6 production can promote skeletal muscle wasting and muscular atrophy." (PMID 32887270, 2020). "Our data suggested a role of systemic IL-6 in ameliorating muscle atrophy." (PMID 29351340, 2018). "Thus, our results suggest that thymic atrophy involves a drop in CLPs production in bone marrow and IL-6-dependent and independent mechanisms that inhibits the differentiation of DN thymocytes." (PMID 28147332, 2017). "Moreover,intrathymic gene expression for IL-6 was significantly up-regulated, whichcontributes to acute thymic atrophy." (PMID 21437240, 2011). "However, our data imply that IL-6 and NT-proBNP can only serve as markers for thymic atrophy rather than being causative factors for DP depletion." (PMID 38393459, 2024).
Atrophy (continued). "Cardiac atrophy and dysfunction results from an abnormally altered metabolism (e.g., MHC shift, insulin deficiency), leading to an imbalance in protein synthesis and degradation, increased systemic inflammation via upregulation of IL‐6 and TNFα, as well as altered energy availability." (PMID 37654192, 2023). "Skeletal muscle tissue levels of IL-6 and TNF-α in the atrophy group were higher than control, and treatment with HRW significantly prevented the rise in tissue levels of these inflammatory markers compared to the atrophy group." (PMID 37895907, 2023). "The results showed that, after 7-days of immobilization, the total expression of inflammatory biomarkers of muscle tissues (IL-6, TNF-α) was significantly reduced in the H2-treatment group compared to the atrophy group (p < 0.05)." (PMID 37895907, 2023). "The results showed that IL-6 protein expression decreased in the group treated with enalapril compared to the atrophy group, but this decrease was not significant." (PMID 38887391, 2024). "IL-6 and suPAR levels were not altered in Hyper/Mix or Atrophy compared to Non-Lipo, but IL-6 (p = 0.21) and suPAR (p = 0.17) were higher in Non-Lipo than Controls, though not significantly." (PMID 26244048, 2015). "IL-6 and TNF-α levels were elevated in both plasma and thymus tissues at 24 h post-CLP, which could imply a potential role of inflammatory processes in acute thymic atrophy." (PMID 40715082, 2025).